TNF (tumor necrosis factor)
Diseases named in the same sentence as TNF in open-access papers (continued):
Sharing a sentence is not in itself a finding about the gene and the disease.
tumor (continued). "Tumor necrosis factor (TNF) is a cytokine closely linked to the tumor microenvironment, where it induces a persistent state of inflammation." (PMID 40699726, 2025). "Man promotes tumor‐associated macrophages toward an antitumorigenic activity in a MC38 liver colorectal cancer model by secretion of TNF‐α, IL ‐1β, and IL ‐6 in the tumor microenvironment." (PMID 39950558, 2025). "In contrast, M1-like macrophages are associated with anti-tumor immunity, partly through the secretion of pro-inflammatory cytokines like TNF, while their functional state remains influenced by dynamic environmental signals." (PMID 40433363, 2025). "In brain tumors, M1 macrophages can directly phagocytose or kill tumor cells through antibody-dependent cytotoxicity and cause vascular damage and tumor necrosis by generating a variety of cytokines, such as IL-1, IL-6, IL-12, IL-23, TNF-α, NO and ROS." (PMID 40303994, 2025). "In mouse models, both IFNγ and TNFα were found to be required for the killing of antigen‐loss variant tumor cells in established tumors." (PMID 40178291, 2025). "Tumor-associated neutrophils isolated from a murine lung cancer model promoted immunosuppression by robustly inducing CD8+ T cell apoptosis through the TNFα pathway, a process that involves nitric oxide (NO) production." (PMID 41254689, 2025). "Within the tumor microenvironment, tumor cells and associated stromal cells, such as macrophages and fibroblasts, secrete pro-inflammatory cytokines (e.g., IL-6, TNF-α, IL-1β)." (PMID 39836268, 2025). "TNF-α was initially known as a factor causing tumour necrosis, but it is now recognized as a major regulator of the inflammatory response." (PMID 40142992, 2025). "For example, the Tumor Necrosis Factor (TNF) pathway was originally annotated based on its association with observed tumor necrosis, while it is multifunctional across diverse physiological processes in the body." (PMID 40843781, 2025). "Overexpression of TNF-α mRNA and IL-1β has been associated with increased tumor growth and invasion, both in epithelial and metastatic CRC." (PMID 41042771, 2025). "This divergence suggests that TNF-α (like CEA) is closely associated with tumor burden in advanced disease, while CRP—an acute-phase reactant—increases with inflammation more generally and less dramatically with stage." (PMID 40299527, 2025). "Significant T-cell expansion and activation; poorer PFS linked to elevated tumor-promoting cytokines (e.g., TNFα, IL6)." (PMID 40433369, 2025). "Hezaveh's experiments found that in pancreatic ductal adenocarcinoma (PDAC), removing dietary tryptophan reduces AhR activity in tumor‐associated macrophages (TAMs) and promotes the accumulation of TNF‐α+IFN‐γ+CD8+ T cells in the tumor." (PMID 40103267, 2025). "IBD treatment often involves immunomodulators like thiopurines or methotrexate and TNF-α antagonists, which can increase cancer risk through DNA alterations, impaired immune control, or reduced tumor surveillance." (PMID 39968296, 2025). "Functional assays in multiple HCC cell lines and mouse models showed that increasing HPX levels reduced tumor growth and promoted programmed cell death through mitochondrial pathways linked to tumor necrosis factor-α." (PMID 41008813, 2025). "To evaluate potential off-target effects, we quantified serum levels of IL-6, TNFα, and TGFβ, the key cytokines associated with tumor progression." (PMID 40475010, 2025). "Further showing the activation of several signaling pathways associated with tumor cell death, including NF-κB, TNF, and JAK-STAT pathways, was enrichment analysis." (PMID 40568960, 2025). "By the interference with the production of NF-κB in T cells, T cells become more susceptible to TNF-α-mediated apoptosis, which is the way that tumor cells induce apoptosis of T cells." (PMID 40940890, 2025). "In the tumor microenvironment, tumor‐associated macrophages have been shown to acquire a lymphangiogenic phenotype in response to TNFα signaling." (PMID 40815083, 2025).
tumor (continued). "MAIT cells exhibit an upregulated PD-1 expression, a downregulated CD45RA-CCR7- effector memory subset, impaired IFN-γ and TNF-α production, and begin favoring a cytokine profile (IL-8) linked to tumor progression." (PMID 40746558, 2025). "Tumor-associated macrophages (TAMs) release tumor necrosis factor-alpha (TNF-α), creating a positive feedback loop that sustains NF-κB activation." (PMID 40075635, 2025). "Tumor-associated inflammation, characterized by elevated TNF-α, IL-6, and IL-1β, was effectively suppressed in both colon tissue and systemic circulation." (PMID 41199821, 2025). "The molecular analysis in this study revealed that immune‐related pathways, including interferon (IFN) and TNFα signaling, were upregulated in low‐risk patients, suggesting a more robust anti‐tumor immune response." (PMID 39985379, 2025). "It has been shown that proinflammatory cytokines released by immunological or tumour cells during CC, such as interleukin‐6 (IL‐6), tumour necrosis factor‐α (TNF‐α) and interleukin‐1 (IL‐1), cause muscle atrophy by activation of NF‐κB pathways." (PMID 40170230, 2025). "High TNF-α expression is associated with poor prognosis and is known to promote tumor growth and EMT, thereby enhancing tumor invasiveness." (PMID 40558596, 2025). "Conversely, tumor-associated macrophages (M1-type) secrete tumor necrosis factor-alpha and nitric oxide to eliminate tumor cells and bolster T cell-mediated immune responses." (PMID 39781524, 2025). "Our analysis of the relationship between tumor size and tumor secretions revealed that larger tumors were associated with higher levels of TNF-α, TNF-R2, IL-1α, IFN-α, MIP-1β, and IL-21." (PMID 39923035, 2025). "ELISA assays performed on tumor-associated immune cell supernatants revealed that IL-6 and TNF-α secretion was significantly increased in the Bacilli group." (PMID 40693141, 2025). "P.g. was implicated in OSCC recurrence by upregulating DOK3 protein in tumor-associated macrophages, potentially activating TNF and MAPK pathways." (PMID 40924302, 2025). "IL-6 and TNF-α, which are closely associated with chronic inflammation, are significantly reduced by exercise, alleviating inflammation in the tumor microenvironment." (PMID 40370453, 2025). "Inflammatory cytokines (TNF-α, IL-1, IL-6) at tumor sites create a pro-autoimmune milieu where the immune system generates AAb against tumor-associated targets, potentially increasing autoimmune risk." (PMID 41367866, 2025). "During inflammation, macrophages and tumor-associated cells secrete TNF-α and IL-1β, activating the NF-κB pathway and inducing COX-2 expression." (PMID 40978482, 2025). "has shown that TNF-α levels in the tumor tissues of NPC patients are associated with poor prognosis." (PMID 40040692, 2025). "Ghrelin, in particular, is implicated in tumor advancement and reduced survival rates, while leptin is known to stimulate the production of pro-inflammatory cytokines TNF-α and IL-6, thereby facilitating cancer cell proliferation." (PMID 39980544, 2025). "TNF-α is one of the key factors closely associated with cholesterol metabolism and the tumor microenvironment." (PMID 41450917, 2025). "CTLs are crucial in anti-tumor immunity, eliminating mutated or tumor cells through perforin-granzyme and Fas-FasL/TNF-TNFR pathways." (PMID 40264780, 2025). "TNF-α is a crucial component of both innate and acquired immunity, capable of inducing apoptosis in tumor-associated cells, resulting in tumor cell destruction." (PMID 40528960, 2025). "tnfa encodes TNF-α, a proinflammatory cytokine involved in immune regulation, inflammatory response, apoptosis, and anti-tumor processes." (PMID 40137482, 2025). "IgE binding to its receptors induces tumor-associated macrophages (TAMs) and monocytes to secrete high levels of cytokines, such as TNF-α, IL-1β, and MCP-1, which enhance ADCC against tumor cells." (PMID 41567205, 2025).
tumor (continued). "In the presence of macrophages releasing TNF-α and IL-1, tumor cells with a deficiency in de novo pyrimidine synthesis showed enhanced levels of PtdSer, a major eat-me signal, potentiating macrophage-mediated elimination in vitro and in mouse models." (PMID 41243973, 2025). "SFV encoding TNFα and IFNγ are expected to inhibit the pro-tumorigenic effect of cancer cells and enhance macrophage anti-tumour gene expression, promoting an M1-like phenotype." (PMID 40547518, 2025). "Several studies identified proteins such as Cyfra 21-1, Cathepsin B, AKR1B10, IL-10, IL-13, and TNF-α as being associated with tumor burden, histological grade, or recurrence risk." (PMID 41149126, 2025). "The enrichment of the inflammatory response gene set aligns with the KEGG results showing activation of TNF and IL-17 signaling, both of which are critical regulators of tumor-associated inflammation." (PMID 41155419, 2025). "Tumor‐associated macrophages are the main source of TNF‐α secretion, which initiates chronic inflammation." (PMID 39803280, 2025). "This functional dichotomy aligns with the known activities of these mediators: where TNF supports cytotoxic immune responses associated with anti-tumor effects, VEGFA is related to angiogenesis." (PMID 41465542, 2025). "On the contrary, it was negatively correlated with cytokine‐encoding related genes such as IFNG, GZMB, PRF1, and TNF in most tumor types." (PMID 40013761, 2025). "Overactivation of the TNFα signaling via the NFκB pathway has been linked to tumor progression, with excessive activation driving tumor cell proliferation." (PMID 40260225, 2025). "The cell cycle and PI3K-Akt pathways are particularly associated with tumor cell proliferation, migration, and survival, while NF-kappa B and TNF signaling pathways are linked to immune responses and inflammation." (PMID 40661083, 2025). "Regulatory M2b macrophages express pro-inflammatory cytokines such as IL6 and TNFα and have been found to be a subset of tumor-associated macrophages (TAMs) that promote growth, invasion, and recurrence of tumors." (PMID 40470186, 2025). "On the other hand, we found several enriched phenotypes associated to the tumor microenvironment, such as tumor necrosis factor secretion." (PMID 40759978, 2025). "At high concentrations, TNF-α can directly kill tumor cells, but it will also cause severe inflammatory reactions and tissue damage." (PMID 40183013, 2025). "CD8 T cells rely on cytokines such as TNF to carry out their cytotoxicity against tumors, and recent findings link select tumor mutations in the TNF pathway to increased T cell killing, in a manner dependent on RIPK1 kinase." (PMID 41315176, 2025). "In the case of low miR-21-5p expression, inflammatory infiltration decreased and fewer tumor-associated inflammatory cytokines, such as TNF-α, IL-6, IL-17A and IL-21, were produced." (PMID 40535722, 2025). "Stress signals such as hypoxia, DNA damage, and pro-inflammatory cytokines (e.g., IFN-γ and TNF-α) upregulate IL-15 expression in tumor-associated macrophages and dendritic cells." (PMID 40299429, 2025). "For instance, TNF-α-driven NF-κB activity in macrophages promotes tumor-associated inflammation and immunosuppression, whereas epithelial NF-κB is essential for barrier maintenance and epithelial function." (PMID 40558596, 2025). "TNF alpha is implicated in numerous functions: inducing fever, apoptosis, necrosis, tumor genesis, progression, and systemic inflammatory reactions." (PMID 41155766, 2025). "Previous studies have shown that tumor-associated macrophages can secrete inflammatory cytokines such as TNF-α and IL-6, activating the STAT3 signaling pathway and thereby promoting chemotherapy resistance in OS cells." (PMID 41285805, 2025). "At the same time, IL-6 and TNF-α secreted by TAMs (tumor-associated macrophages) promote ROS accumulation through NOX2 activation, forming a vicious cycle of oxidative stress-ferroptosis." (PMID 40535125, 2025).
tumor (continued). "In breast cancer organoid models and tumor-associated macrophage cocultures, UA suppressed proinflammatory cytokines, including IL-6 and TNF-α, creating a tumor microenvironment with reduced inflammation." (PMID 40568370, 2025). "TNF-α activates caspase pathways, causing death in tumor cells and attracting immune cells to the tumor, leading to a localized antitumor response." (PMID 40309351, 2025). "Tumor cells, when induced by these mutated strains, can secrete antitumor cytokines such as IL-1β, IL-18, and TNF-α." (PMID 40430828, 2025). "Tumor cell proliferation has been inhibited by the downregulation of inflammatory cytokine (TNF-α) associated with the vascular endothelial growth factor pathway." (PMID 39944222, 2025). "In univariate and multivariate analyses, pretreatment inflammatory markers, including TNF-α and IL-12p40, as well as total metabolic tumor volume (TMTV), associated with disease progression." (PMID 40536814, 2025). "Collectively, these findings point to the specificity of TNF-α–tumor marker associations in active malignancy." (PMID 40299527, 2025). "Among them, IL-1β and TNF-α contribute to tumor chemotherapy resistance and are associated with poor prognosis of chemotherapy." (PMID 39972411, 2025). "On the other hand, glycolytic metabolism fosters the PD-L1 expression on macrophages by causing the secretion of pro-inflammatory cytokines TNF-α and IL-1β, leading to tumor immune escape." (PMID 39897050, 2025). "It features cancer‐specific replication controls and includes transgenes that encode IL‐2 and TNF‐α to boost T‐cell growth, trafficking, and tumor apoptosis." (PMID 40726054, 2025). "Correlation of the tumor size values with the secreted levels of cytokines in the TNF-α High group identified a moderate association of tumor size with IP-10 (r = 0.488, P = 0.049)." (PMID 39923035, 2025). "Clinically, high TNF-α expression in tumor tissues or blood has been associated with adverse features such as lymph node involvement and early recurrence in various cancers." (PMID 40299527, 2025). "Monocytes were observed transitioning into tumor-associated macrophages, secreting factors such as TNF-α and VEGF to facilitate both tumor expansion and angiogenesis." (PMID 38571504, 2024). "Exo improves the stability of Bilberry-derived anthocyanins, causes inhibition of TNFα-induced NF-κB activation in tumor cells, and exerts anti-inflammatory and anti-tumor effects." (PMID 39464892, 2024). "In melanoma, elevated levels of IL-6 and TNF-α have been associated with increased tumor growth and poor prognosis." (PMID 39200315, 2024). "SCFAs such as butyrate can reduce the intratumoral levels of T cells, INF-γ and TNF-α and cause the tumor cells to proliferate at a slower rate with better immune response." (PMID 39210613, 2024). "Anti-TNF therapy is associated with an increased risk of infection and tumor progression due to the existence of two structurally different TNF receptors that have opposing functions." (PMID 38540714, 2024). "Consistent with this notion, cisplatin-induced GSDME-dependent pyroptosis increased the levels of TILs and cytokines associated with T cell activation (TNFα and IFNγ) in the tumor tissue." (PMID 38391959, 2024). "Regarding the vascular system, OVs disrupt tumor vasculature by infecting tumor-associated endothelial and proximal tumor cells, triggering an inflammatory response and the release of TNF-α and IFN-γ." (PMID 38992667, 2024). "Recent studies showed that loss of TNFα sensitivity led to tumor immune evasion and was associated with reduced infiltration of immune cells, suggesting that TNFα-mediated cell death was essential for promoting antitumor immunity." (PMID 38195677, 2024). "Apoptosis of tumor cells was associated with augmented expression of TNF-α, Fas, and FasL, as well as suppression of the anti-apoptotic NF-κB and mTOR pathways." (PMID 39683650, 2024).
tumor (continued). "Specific changes in cytokine levels in the serum, including interleukins and TNFα, have been linked to disease severity, tumor progression, and therapeutic response in children with ALL and AML." (PMID 38927907, 2024). "Tumours with high immunoproteasome expression have higher cytotoxic immune cell infiltration and are associated with the upregulation of INFγ and TNFα pathways in tumour cells." (PMID 39140283, 2024). "This included pro-inflammatory cytokines such as IL6 and IL8, typically elevated in the tumor microenvironment, and TNF-alpha, known for its association with T-cell activation." (PMID 38383454, 2024). "Sustained activation of NF-κB by TNF causes stimulation of cancer cell proliferation, prevents apoptosis during drug resistance, and enhances angiogenesis and tumor metastasis." (PMID 39652576, 2024). "In summary, these data indicate that IL‐17A and TNF cooperatively reprogram mesothelial cells towards a mesenchymal phenotype, resulting in a loss of monolayer integrity and increased tumor cell attachment." (PMID 38566518, 2024). "TNF-α within the tumor microenvironment can cause tumor proliferation as well as metastasis through EMT activation." (PMID 39427065, 2024). "High doses of lo-regional TNF-α can cause hemorrhagic necrosis by selectively destroying tumor vasculature and generating specific T-cell anti-tumor immunity." (PMID 38553639, 2024). "TNF-α induces cell cytotoxicity in fibroblasts while VEGF has a mitogenic effect on endothelial cells implicated in tumor angiogenesis." (PMID 38533506, 2024). "The TNF-α and NF-kappa B pathways are closely linked to tumor progression and resistance to treatment." (PMID 38468267, 2024). "The results of in vitro and in vivo studies have shown the pro-tumor effects of TNF-α, and this cytokine’s increased expression is associated with poor prognosis in patients with some types of cancer." (PMID 39408920, 2024). "TNF-α is one of the pleiotropic cytokines, playing a central role in the tumor-associated cytokine network." (PMID 38656555, 2024). "Beyond its direct tumoricidal effects under specific conditions, TNF has been implicated in promoting tumor progression." (PMID 39034318, 2024). "High local concentrations of IFNγ and tumor necrosis factor α (TNFα), secreted by tumor-associated macrophages, prompt cancer cells to express programmed death ligand 1 (PD-L1)." (PMID 39744013, 2024). "In this model, combinations of ATRA and radiotherapy induce the differentiation of tumor infiltrated monocytes into inflammatory iNOS/TNFα-producing macrophages, contemporaneously enhancing the priming/activation of tumor associated CD8+/CD4+ T-cells." (PMID 38360674, 2024). "Because of persistent tumor cells, CD8 + TILs lose their ability to produce triple cytokines TNFα, IL-2, and IFNΥ responsible for showing the PD-1-Tim-3 + phenotype, an effector memory subset causing tumor rejection." (PMID 39692821, 2024). "The N1 and N2 subsets exhibit plasticity during tumor progression, with the protumor effects of N1 associated with TNFα, ICAM-1, ROS, Fas, and reduced arginase expression." (PMID 38474175, 2024). "Through the TNF pathway, tumor-associated neutrophils induce CD8+ T-cell apoptosis, further exacerbating their immunosuppressive phenotype." (PMID 38358352, 2024). "In the GSEA results, TNF-α signaling via NF-κB was significantly associated with genes upregulated only in the recurrent tumor region." (PMID 39135097, 2024). "TNF-α is a crucial cytokine produced by tumor-associated macrophages (TAMs), with dual roles in the TME." (PMID 39766056, 2024).